CSP2 (CS pseudogene 2)
Gene: Processed pseudogene on chromosome 3 (107,327,830 to 107,329,197, reverse strand). Ensembl gene ENSG00000241218.
Diseases named in the same sentence as CSP2 in open-access papers:
CSP2 is named in the same sentence as 5 diseases in open-access papers, as found by Europe PMC text mining. Sharing a sentence is not in itself a finding about the gene and the disease. The quoted sentences say what the papers report.
pneumococcal infection (1 paper, 2022). Infections with bacteria of the species streptococcus pneumoniae. "Mice exhibited a greater survival rate following CSP2-E1Ad10 treatment compared with the negative control vehicle (PBS), highlighting the potential of CSP2-E1Ad10 in reducing pneumococcal infections caused by group 2 pneumococcus." (PMID 35920042, 2022).
renal carcinoma (1 paper, 2022). A carcinoma arising from the epithelium of the renal parenchyma or the renal pelvis. "The CSP2 subtype predicted a poorer prognosis of renal cancer patients than the CPCS1 subtype, which was consistent with previous data." (PMID 36581992, 2022).
cancer (1 paper, 2022). A tumor composed of atypical neoplastic, often pleomorphic cells that invade other tissues. "The CSP2 subtype was correlated with CD8 + T cells, Tregs, cancer-associated fibroblasts and NK cells." (PMID 36581992, 2022). "The CSP2 subtype, but not the CPCS1 subtype, was activated in tumorigenicity and cancer progression." (PMID 36581992, 2022).
immune dysfunction (1 paper, 2022). "The CSP2 subtype displayed more CD8 + T cells, lacked activated dendritic cells and had reduced DNA damage repair ability, which caused immune dysfunction." (PMID 36581992, 2022).
tumor (1 paper, 2022). "The CSP2 subtype shared a higher tumor mutation burden and low tumor stemness index but led to a low ICI therapy response and tumor immunity dysfunction state." (PMID 36581992, 2022). "The CSP2 subtype lacked activated dendritic cells, which prompted the reduction of identifying tumor cells." (PMID 36581992, 2022).